MST1R (macrophage stimulating 1 receptor)
Description:
Receptor tyrosine kinase that transduces signals from the extracellular matrix into the cytoplasm by binding to MST1 ligand. Regulates many physiological processes including cell survival, migration and differentiation. Ligand binding at the cell surface induces autophosphorylation of RON on its intracellular domain that provides docking sites for downstream signaling molecules. Following activation by ligand, interacts with the PI3-kinase subunit PIK3R1, PLCG1 or the adapter GAB1. Recruitment of these downstream effectors by RON leads to the activation of several signaling cascades including the RAS-ERK, PI3 kinase-AKT, or PLCgamma-PKC. RON signaling activates the wound healing response by promoting epithelial cell migration, proliferation as well as survival at the wound site. Also plays a role in the innate immune response by regulating the migration and phagocytic activity of macrophages. Alternatively, RON can also promote signals such as cell migration and proliferation in response to growth factors other than MST1 ligand.
Synonyms: CD136; PTK8; RON; CDw136; NPCA3; SEA; p185-Ron
Tractability: Small molecule: a drug acting on it is in phase 1 trials; a structure with a bound ligand is known; a high-quality ligand is known; it belongs to a druggable protein family. Antibody: a drug acting on it is in phase 2 or 3 trials; its Gene Ontology location is reachable by antibodies, with high confidence; UniProt predicts a signal peptide or a membrane-spanning region. PROTAC: UniProt records ubiquitination sites on it; ubiquitination databases record sites on it; a small molecule that binds it is known.
Target class: Enzyme; Tyrosine protein kinase Met family; TK protein kinase group; Kinase; Protein Kinase
Chemical probes: MK-8033 (high quality), PD083398
Gene: Protein-coding gene on chromosome 3 (49,886,902 to 49,906,130, reverse strand). Ensembl gene ENSG00000164078.
Subcellular location: Membrane
Subcellular location (Human Protein Atlas): Cytosol
Pathways (Reactome):
Signal Transduction: Signaling by MST1
Gene Ontology:
Molecular function: enzyme binding; protein binding; macrophage colony-stimulating factor receptor activity; transmembrane receptor protein tyrosine kinase activity; ATP binding; protein kinase activity; protein tyrosine kinase activity
Biological process: positive regulation of MAP kinase activity; positive regulation of phosphatidylinositol 3-kinase/protein kinase B signal transduction; response to virus; cell migration; cell surface receptor protein tyrosine kinase signaling pathway; defense response; nervous system development; phagocytosis; positive regulation of cell population proliferation; signal transduction; single fertilization; macrophage colony-stimulating factor signaling pathway
Cellular component: cell surface; plasma membrane; receptor complex; membrane; stress fiber; vacuole
Genetic constraint (gnomAD): Loss-of-function variants: 99 observed, 118.74 expected, observed/expected ratio (o/e) 0.83, 90% interval 0.71 to 0.99. The upper end of that interval is the gene's LOEUF score, 0.99, which puts it in group 4 of 6, group 1 being the genes least tolerant of losing a copy. Missense variants: 1,683 observed, 1,891.4 expected, observed/expected ratio (o/e) 0.89, 90% interval 0.85 to 0.93. Synonymous variants: 734 observed, 785.75 expected, observed/expected ratio (o/e) 0.93, 90% interval 0.88 to 0.99.
Homologues: Orthologues: chimpanzee MST1R (99% identical), macaque MST1R (96% identical), rabbit MST1R (82% identical), guinea pig MST1R (78% identical), dog MST1R (76% identical), rat Mst1r (75% identical), pig MST1R (75% identical), mouse Mst1r (74% identical), tropical clawed frog MST1R (42% identical), zebrafish mst1rb (40% identical), zebrafish mst1ra (39% identical). Paralogues in human: MET (34% identical), ROS1 (17% identical), TYRO3 (15% identical), RET (15% identical), AXL (14% identical), MERTK (14% identical), IGF1R (14% identical), INSR (13% identical), ALK (13% identical), INSRR (13% identical), TEK (13% identical), ERBB2 (12% identical), and 41 more.
Diseases named in the same sentence as MST1R in open-access papers:
MST1R is named in the same sentence as 82 diseases in open-access papers, as found by Europe PMC text mining. Sharing a sentence is not in itself a finding about the gene and the disease. The quoted sentences say what the papers report.
breast cancer (33 papers, 2008 to 2025). A primary or metastatic malignant neoplasm involving the breast. "We next asked whether genomic alterations known to drive breast cancer have associations with increased MST1R/MST1 expression." (PMID 35626096, 2022). "According to previous studies, colorectal patients with MLL3 mutation could benefit from ICI therapy, while MST1R signaling promoted therapeutic resistance in ESR1 mutant breast cancer." (PMID 35997004, 2022). "MST1R is notably overexpressed in breast cancer, colorectal cancer, pancreatic cancer, and prostate cancer, exerting a tumor-promoting effect through diverse mechanisms." (PMID 39210450, 2024). "We analyzed a total of 6 genes: ESR1, DRD2, LINE1, MST1R, that we have previously demonstrated to be differentially methylated in prostate and breast cancers." (PMID 36067197, 2022). "KMT2C was a consistent hit across TCGA PanCan and METABRIC datasets but for MST1R only, thus potentially representing a mechanism by which MST1R alone becomes overexpressed in breast cancer." (PMID 35626096, 2022). "MSP binds its receptor, Ron (MST1R), which is expressed on a variety of cells including breast cancer cells." (PMID 33235291, 2021). "Alana L et.al identified that MST1R played a role in promoting osteolytic bone metastasis in breast cancer." (PMID 31897234, 2020). "To address this question, we probed the METABRIC and TCGA datasets on cBioportal for MST1 and MST1R mRNA expression using the PAM50 breast cancer subsets to divide the samples." (PMID 32484599, 2020). "The upregulation of MST1R promotes the progression of many epithelial cancers, including pancreatic, lung, and breast cancer." (PMID 31889904, 2019). "These authors concluded that the pattern of expression and localization of the MST1R protein in FMCs overlay with that of the homologous receptor in human breast cancer." (PMID 29056725, 2016). "Feline MST1R-specific transcript was detected by reverse transcriptase PCR (RT-PCR) in seven of eight analyzed feline mammary carcinomas." (PMID 29056725, 2016). "MST1R transcripts were detected by RT-PCR and the protein by immunohistochemical analysis in the majority of the feline mammary carcinomas examined." (PMID 29056725, 2016). "The Ron receptor tyrosine kinase, also known as macrophage-stimulating 1 receptor (MST1R), is overexpressed in approximately 50% of human breast cancers and is associated with increased metastasis and poor patient prognosis." (PMID 26008979, 2015). "MST1R, on the other hand, has primarily been detected in various tumors, including pancreatic cancer, nasopharyngeal carcinoma, prostate cancer, and breast cancer." (PMID 39478699, 2024). "Given the lack of consistency in expression differences between PAM50 subsets in the METABRIC and TCGA datasets and the lack of difference between histological subgroups, these data indicate that MST1 and MST1R expression is mostly uniform across human breast cancer subtypes." (PMID 32484599, 2020). "In addition, the proto-oncogenic MST1R loci, associated with poor prognosis through potentiation of cell scattering and invasion in breast cancer, were unmethylated in most tumors irrespective of chromosome 3p loss." (PMID 20300172, 2010). "MET also co-signals with other RTKs, such as RON, also widely known as the macrophage stimulating 1 receptor (MST1R), which is overexpressed or constitutively active in more than 50% of human breast cancer cases." (PMID 40560045, 2025). "TCGA and METABRIC gene expression and alteration data were used to query the relationships between MST1R and MST1 in breast cancer." (PMID 35626096, 2022). "A significant positive correlation of MST1R and MST1 with M2 macrophage infiltration and naïve T cell responses was identified by examining the tumor immune microenvironment estimation resource (TIMER) from breast cancer data from TCGA with MST1R and MST1 expression." (PMID 35626096, 2022).
pancreatic cancer (14 papers, 2008 to 2026).
breast tumors (11 papers, 2015 to 2025). "RON, also known as macrophage stimulating-1 receptor, is an RTK often overexpressed in breast tumors and linked to metastasis and poor patient outcomes." (PMID 40281554, 2025). "This was validated in breast tumor tissue through RT-PCR, except for MST1R." (PMID 32710281, 2020). "We found that all ten EMT-related genes were frequently methylated in primary breast tumours, i.e. CLDN18 (100 %), KRT85 (100 %), MIR127 (100 %), MIR433 (100 %), MIR23b (60 %), KRT83 (100 %), MST1R (60 %), BVES (60 %), CLDN6 (50 %) and HOXD10 (55 %)." (PMID 26052355, 2015). "For MST1R expression, statistical differences between PAM50 subsets were only observed in the METABRIC dataset; expression was highest in HER2 breast tumors and lowest in claudin‐low breast tumors." (PMID 32484599, 2020).
prostate carcinoma (11 papers, 2017 to 2025). A carcinoma that arises from epithelial cells of the prostate gland. "In previous studies, immunohistochemical analysis revealed the expression of wild-type MST1R in various cancerous and adjacent cancerous tissues, including pancreatic and prostate cancers." (PMID 40061823, 2024). "We have identified for the first-time macrophage stimulatory protein 1 receptor (MST1R) as a potential target of 2-ME2 in prostate cancer cells." (PMID 33673346, 2021). "2-ME2 treatment inhibited mechanical properties such as adhesion and elasticity that are associated with epithelial mesenchymal transition by downregulating mRNA expression and protein levels of MST1R in prostate cancer cell lines." (PMID 33673346, 2021). "Human tissue validation studies show that MST1R (a.k.a RON) protein levels are significantly elevated in prostate cancer tissues compared to adjacent normal/benign glands." (PMID 33673346, 2021). "One of the genes that we found was significantly associated with prostate cancer, MST1R (Macrophage Stimulating 1 Receptor) or RON, is overexpressed in prostate cancer and various other cancers." (PMID 31748686, 2019).
gastric cancer (6 papers, 2011 to 2023). A primary or metastatic malignant neoplasm involving the stomach. "miR647 modulates FBLN1, FN1, and MST1R genes and has a tumor-promoting role in gastric cancer via repression of TP73." (PMID 34357026, 2021). "Nevertheless, targeting MST1R alone or in a concerted fashion could be an effective therapeutic strategy for the treatment of certain cancerous profiles, including pancreatic and stomach cancers." (PMID 36361696, 2022). "In addition, overexpression of MST1R is also common in patients with stomach cancer." (PMID 36361696, 2022). "Similarly, MST1R had interactions with AKT, AKT1, and MST1, while LTR interacted with IRS1, CBL, PIK3C and SHC1, none of which have been found to be associated with gastric cancer before." (PMID 37287033, 2023). "Furthermore some gastric cancers harbour DNA amplification or overexpression of the RTK MET and its paralogue MST1R and may be treated with MET or MST1R inhibitors." (PMID 21781349, 2011).
ovarian carcinoma (6 papers, 2006 to 2023). A malignant neoplasm originating from the surface ovarian epithelium. "Furthermore, high expression of MST1R (RON) has been linked to cisplatin resistance in ovarian cancer, a principle element in the standard first-line chemotherapy for mesothelioma." (PMID 30863365, 2019). "Several putative oncogenes were differentially expressed in MOC, including the breast tumour kinase BRK (PTK6) not previously implicated in ovarian cancer pathogenesis; and MST1R/RON, a receptor tyrosine kinase associated with proliferation and motility of cancer cells including ovarian carcinoma." (PMID 16508639, 2006). "In our study, we identified the genes with a mutation frequency ranking in the top 5 of 100 PTK genes in EOC, namely, MST1R, INSR, RET, PDGFRB, and PTK7, among which we studied the overlooked oncogenic role of RET in ovarian cancer." (PMID 32293499, 2020).
bladder cancer (5 papers, 2019 to 2025). "miR892b modulates the FBLN1, MYH7B and MST1R genes and is known to influence proliferation, migration, and invasion of bladder cancer cells." (PMID 34357026, 2021). "After performing a series of bioinformatic and machine learning approaches, we identified distinct tumor microenvironment clusters and three bladder cancer specific immune-related genes (EGFR, OAS1 and MST1R)." (PMID 36267410, 2022).
melanoma (4 papers, 2016 to 2021). A malignant, usually aggressive tumor composed of atypical, neoplastic melanocytes. "Ectopic FOXC1 expression induced MST1R expression and promoted migration and invasion of melanoma cells by activating the MST1R/PI3K/AKT pathway." (PMID 29552326, 2018). "Our study also found that FOXC1 induced expression of MST1R and exerted function by MST1R/PI3K/AKT pathway, and that FOXC1 expression was associated with progress and prognosis of melanoma." (PMID 27533251, 2016). "MST1R expression was knockdowned by MST1R siRNAs in FOXC1 overexpression melanoma cells and proliferation, migration and invasion of cells were significantly reduced." (PMID 27533251, 2016). "Taken together, these results suggested that the MST1R/PI3K/AKT pathway was activated in FOXC1 overexpression melanoma cells." (PMID 27533251, 2016). "FOXC1 exerted functional roles by activating the MST1R/PI3K/AKT pathway in melanoma." (PMID 29552326, 2018). "In cervical cancers and melanoma, it was shown that FOXC1 increased MST1R and activated the PI3K/AKT pathway to drive invasion and migration in melanoma cells." (PMID 34540690, 2021). "Taken together, these studies supported the finding that therapeutic targeting of the EGFR/FOXC1/NFκB pathway and PI3K/AKT/mTOR in BLBC, PI3K/AKT/HIF-1α/FOXC1 axis in HCC and MST1R/PI3K/AKT in cervical cancers, melanoma and pancreatic cancers, may provide effective modalities for treatment." (PMID 34540690, 2021).
nasopharyngeal carcinoma (4 papers, 2021 to 2024). A carcinoma arising from the nasopharyngeal epithelium. "Previous studies using WES demonstrated that rare genetic variants in MST1R contribute to Lady Windermere syndrome and nasopharyngeal carcinoma." (PMID 40061823, 2024). "Dai and coworkers found a significant association between variation in the MST1R gene and development of nasopharyngeal carcinoma." (PMID 34357026, 2021).
colorectal cancer (3 papers, 2017 to 2024). A primary or metastatic malignant neoplasm that affects the colon or rectum. "In colorectal cancer cells, soluble factors of epithelial origin were shown to induce a constitutively active splice variant of the macrophage stimulating 1 receptor (MST1R) gene encoding the receptor tyrosine kinase named RON." (PMID 29286307, 2017). "Among these compounds, 10a was identified as the most potent HGFR/MST1R dual inhibitor (HGFR IC50=0.11 μM and MST1R IC50=0.045 μM) with excellent anti-colorectal cancer activity (COLO 205 IC50=0.11 μM)." (PMID 36043496, 2022).
lung carcinoma (3 papers, 2018 to 2021). "The activity prediction algorithm was then implemented for the regulatory networks of six important lung cancer oncogenes (FAK, PXN, MET, RON (MST1R), EPHA2, AXL)." (PMID 29731983, 2018). "For example, the dual MET/MST1R (RON) kinase inhibitor, LY2801653 which is a type-II ATP competitive, slow-off inhibitor binding to the kinase domains of these RTKs, decreased tumor growth and angiogenesis in the lung cancer setting and demonstrated greater efficacy than crizotinib." (PMID 30863365, 2019).
multiple sclerosis (3 papers, 2017 to 2025). A progressive autoimmune disorder affecting the central nervous system resulting in demyelination. "It is unclear whether lower serum MSP contributes to IBD risk, but it is reported that MST1R expression was significantly downregulated in other immune disease (ie, multiple sclerosis) in both mouse and human subjects." (PMID 28129359, 2017).
Obesity (3 papers, 2016 to 2022). Accumulation of substantial excess body fat. "In ConvR HFD mice liver, 17 genes DNA methylation changes including Ube2l3, Etv5, Lrp1, and Nudt3 were determined related to obesity and 11 genes DNA methylation changes including Exoc312, Mst1r, Prkch, and Arhgap26 were determined related to Type 2 diabetes (T2D) in the previous study." (PMID 35458198, 2022).
Pectus excavatum (3 papers, 2020 to 2022). A defect of the chest wall characterized by a depression of the sternum, giving the chest ("pectus") a caved-in ("excavatum") appearance. "Mutations in the macrophage-stimulating-1 receptor (MST1R) gene have been implicated in the development of “Lady Windermere syndrome”, in which NTM-PD occurs in patients who have a slender body habitus, pectus excavatum and scoliosis." (PMID 34835346, 2021).
prostate tumor (3 papers, 2023 to 2025). "In a recent study, loss of prostate epithelial macrophage stimulating 1 receptor (MST1R) was shown to suppress M2 marker expression, while epithelial MST1R activation upregulated its own expression in macrophages, in a positive feedback mechanism, driving prostate tumor growth." (PMID 37090711, 2023).
congenital heart disease (2 papers, 2024 to 2025). A heart disease that is present at birth. "The combination of clinical evaluation, genetic analysis and cellular functional assays collectively suggest that MST1R may be involved in the pathogenesis of certain types of congenital heart disease." (PMID 40061823, 2024).
hepatoblastoma (2 papers, 2018 to 2022). Hepatoblastoma (HB) is a malignant hepatic tumor and is the most common pediatric liver cancer. "Thus, MST1R expression and the association of DNA methylation status differ between HCC and hepatoblastomas." (PMID 29566670, 2018). "On the other hand, a recent study reported downregulation of MST1R and hypermethylation of the TSS upstream region in human hepatoblastomas." (PMID 29566670, 2018). "Limited genome-wide methylation analysis by HM450 found that differentially methylated genes were involved with liver cell differentiation and cancer, and four tumor suppressor genes (GPR180, MST1R, OCIAD2, and PARP6) were potentially related to progression in hepatoblastomas." (PMID 36212481, 2022).
non-small cell lung carcinoma (2 papers, 2021 to 2023). A group of at least three distinct histological types of lung cancer, including non-small cell squamous cell carcinoma, adenocarcinoma, and large cell carcinoma. "Notably, crizotinib, the inhibitory drug of MST1R, has been used to treat non-small cell lung cancer." (PMID 38102678, 2023).
viral infection (2 papers, 2021 to 2025). "Pathogenic heterozygous germline variants in MST1R, which encodes the macrophage-stimulating 1 receptor critical for host defense against viral infections, are strongly linked to the early onset of NPC." (PMID 40697386, 2025).
acinar adenocarcinoma (1 paper, 2022). "While, gene mutations including PTEN, MST1R, and PIK3CA were noted during transdifferentiation from acinar adenocarcinoma to LCNEC." (PMID 36507119, 2022).